TSHR (thyroid stimulating hormone receptor)
Diseases named in the same sentence as TSHR in open-access papers (continued):
Sharing a sentence is not in itself a finding about the gene and the disease.
Autoimmunity (58 papers, 2005 to 2026). The occurrence of an immune reaction against the organism's own cells or tissues. "In thymus, the lower TSHR expression triggered by the susceptible genotype would likely facilitate escape from central tolerance and increases the risk of autoimmunity to TSHR." (PMID 28421036, 2017). "Reduction in thymic expression of TSHR may contribute to sustained escape of pathogenic T cells from the centre and an increased risk of TSHR autoimmunity." (PMID 30384852, 2018). "However, a couple of somatic TSHR variants that had been proposed as the cause of autoimmunity, including Asp36His and Pro52Thr, were later demonstrated to be polymorphisms that were also frequently present in healthy people." (PMID 30319546, 2018). "Joint thyroid eye clinics providing care for the broad TSHR autoimmunity spectrum will be the ideal setting for patient management; however, these are quite scarce outside of Europe." (PMID 40622195, 2025). "This provides an increased opportunity for the development of autoimmunity against the upregulated TSHR." (PMID 38311752, 2024). "Patients with thyroid-directed autoimmunity have demonstrated significant elevations in Th1, normal or low Th2 numbers, and high IgG antibodies to thyroid stimulating hormone receptor (TSHR)." (PMID 35736648, 2022). "Of note, the suppression of TSHR autoimmunity was accompanied by a decrease in CD25+ T cells while subsets CD25+Foxp3+ Tregs were increased." (PMID 32399893, 2020). "Systemic inflammation and TSHR autoimmunity are key pathological features of GD." (PMID 40265938, 2025). "Therefore, we investigated the effects of low-dose MMI, B. fragilis, and propionate, either alone or in combination, on systemic inflammation and TSHR autoimmunity in GD mice." (PMID 40265938, 2025). "Whether the observed changes in Treg proportions represent their role in improving TSHR autoimmunity remains to be proven by further studies addressing the functional activity of the different T-cell subsets in the model." (PMID 32399893, 2020). "The detection of thyroid-stimulating hormone-receptor (TSH-Receptor) antibodies (TSH-R-Abs) may confirm the autoimmunity and the diagnosis of TAO." (PMID 29736194, 2018). "In addition also different approaches to develop TSHR autoimmunity in animals may effect the sex-specific outcome." (PMID 30166557, 2018). "At age 11, routine blood tests for thyroid function and autoimmunity showed decreased thyroid-stimulating hormone (TSH) levels and significantly elevated TSH receptor (TSHR) antibodies." (PMID 37635986, 2023). "In humans, and in mice that spontaneously develop autoimmunity to all three thyroid autoantigens, autoantibodies develop first to Tg and later to TPO and the TSHR A-subunit." (PMID 29326719, 2017). "In the early stages, direct administration of TSHR-expressing cells is employed; however, due to its relatively low efficiency in inducing autoimmunity, this approach is not currently utilized." (PMID 39280007, 2024).
Graves’ orbitopathy (55 papers, 2013 to 2026). "Although TSHR-21-42 was initially designed for thyroid-associated ophthalmopathy, it holds great potential as a tool for TSHR-targeting nanomaterials." (PMID 40532044, 2025). "The insulin-like growth factor 1 receptor (IGF1R) is an RTK shown to have crosstalk with TSHR in brow fat and orbital fat of patients with thyroid-associated ophthalmopathy." (PMID 34524974, 2021). "Researchers have reported that different microbiomes in mice can lead to different presentations of GD and Graves’ ophthalmopathy after injection with a human thyroid-stimulating hormone receptor (hTSHR) eukaryotic expression plasmid." (PMID 36865531, 2023). "Graves’ ophthalmopathy (GO) is an autoimmune inflammatory disease in which TSHR-stimulated antibodies and TSHR affect cells in surrounding tissues." (PMID 34051850, 2021). "Graves’ ophthalmopathy (GO) is an autoimmune inflammatory disorder in which TSHR-stimulating antibody and TSHR influence several different cells in the periorbital tissue." (PMID 31399042, 2019). "GD is characterized by a high level of thyroid hormone, a diffuse goitre, a positive test for thyroid stimulating hormone receptor antibody (TRAb), Graves ophthalmopathy and anterior tibia mucous oedema." (PMID 27456991, 2016).
Hashimoto thyroiditis (54 papers, 2009 to 2025). An autoimmune disorder caused by the production of autoantibodies against thyroid tissue. "Among families with primary patients with CH referred to our center, five consanguineous families with multiple affected individuals with non-autoimmune hypothyroidism carried inactivating TSHR variants." (PMID 40391015, 2025). "TSHR-stimulating antibodies cause GD; however, their function in persons with Hashimoto's thyroiditis (HT) is contested." (PMID 36514581, 2022). "HLA-DR3, cytotoxic T-lymphocyte-associated protein 4 (CTLA-4), and the TSHR genes were shown to be major susceptibility genes for GD and Hashimoto’s thyroiditis (HT) using the candidate gene approach." (PMID 31066758, 2019). "The samples were collected from four untreated GD and two autoimmune hypothyroidism patients, which favored the results of the Anti‐TSHR assay." (PMID 34752648, 2021). "Regulatory T cells (Treg) are a major factor in intermolecular immune response expansion, both from TSHR to TPO and Tg and alteration of hyperthyroid into Hashimoto's thyroiditis with massive thyroid lymphocytic infiltration, which causes hypothyroid state." (PMID 24198979, 2013). "This would be similar to the pathologic mechanism through which the autoantibodies to thyroglobulin, thyroid peroxidase and/or the thyroid-stimulating hormone receptor function in Hashimoto's thyroiditis." (PMID 21521495, 2011). "The finding that some antibodies to the TSHR which compete for TSH binding but do not initiate normal TSH signaling but rather block TSH induced stimulation identifies the class of TSHR blocking antibodies and mostly reported in a segment of patients with Hashimoto’s thyroiditis." (PMID 35909553, 2022). "While canine hypothyroidism is generally thought to be caused by lymphocytic thyroiditis or idiopathic atrophy, it is plausible that changes in expression of DIO2 or TSHR could influence its development." (PMID 32631225, 2020). "They identified a haplotype associated with GD (OR = 1.7), but not with autoimmune hypothyroidism, and concluded that TSHR is a GD-specific susceptibility locus." (PMID 28421036, 2017). "Certainly, high thyroidal radioactive iodine uptake is seen in early Hashimoto's thyroiditis but usually under the condition of an elevated TSH and TSHR activation." (PMID 30319546, 2018). "Preoperative PB TSHR mRNA expression levels were significantly associated with patient age, capsular invasion status, lymph node metastasis status, and BRAFV600E mutation status (P < 0.05) but not gender, tumor size, number of cancer foci, or Hashimoto thyroiditis status." (PMID 29088773, 2017).
goiter (33 papers, 2009 to 2025). Enlargement of the thyroid gland usually caused by lack of iodine in the diet, hyperthyroidism, or thyroid nodules. "Sporadic TSHR mutations were found to cause severe thyrotoxicosis and goiter with onset in the neonatal period or infancy." (PMID 21274318, 2010). "In the biallelic group, we found that 81.8% (18/22) of cases (16 cases of GIS, 4 cases of goiter, and 2 cases of TD) harbored variants in DUOX2, two GIS cases had DUOXA2 variants, and two TD cases had TSHR variants." (PMID 34539567, 2021). "In response to the TSHR genetic immunization, it was observed that more than 90% of the genetically immunized mice showed obvious goiter and thyroid hypertrophy." (PMID 28319174, 2017). "Earlier mutational screening excluded thyroid synthesis-related genes, the TSHR and FOXE1, to be the cause of CH and goiter in these two patients." (PMID 24745015, 2014). "Consequently, direct stimulation of TRAbs on the TSHR induces inappropriately high secretion of thyroid hormones, goiter, and extrathyroidal manifestations (especially orbitopathy and/or myxedema)." (PMID 41283242, 2025). "Another explanation is that many factors may affect the remission such as severe biochemical disease, male sex, young age (< 40 years), high concentrations of TSHR antibodies, presence of large goiter, and smoking." (PMID 37409226, 2023). "Despite elevated TSH levels, several of our non-TSHR mutation-positive cases (mainly detected in the neonatal period) did not exhibit goiter." (PMID 27525530, 2016). "Some reports suggested the predictive role of the absence of goiter, serum TSHR Ab level at time of GD diagnosis or shorter TSHR Ab normalization time." (PMID 36988246, 2023). "For 75% of the TSHR-positive cases (F6, F14, F15, F34), no goiter was detected, but hypoplasia was noticed in two infants after scintigraphy." (PMID 34248839, 2021). "In our opinion, in hypothyroid patient without goiter, anti-TSHR antibodies should be the obvious element of laboratory workshop." (PMID 32733376, 2020). "It is necessary to conduct prospective studies evaluating the actual frequency of anti-TSHR antibodies and pituitary enlargement in children with extremely high TSH, especially without goiters." (PMID 32733376, 2020). "It is necessary to conduct prospective studies evaluating the actual frequency of anti-TSHR antibodies and pituitary enlargement in children with extremely high TSH, especially those presenting without goiters." (PMID 32733376, 2020).
congenital hypothyroidism (30 papers, 2011 to 2026). A thyroid hormone deficiency present from birth. "More than 40 kinds of distinct loss-of-function mutations in the TSHR gene have been reported as causative defects in congenital hypothyroidism." (PMID 41393297, 2025). "Loss- and gain-of-function mutations in the TSHR lead to TSH resistance with congenital hypothyroidism (OMIM 275200) or autosomal dominant hyperthyroidism (OMIM 609152), respectively." (PMID 41393297, 2025). "Thyrotropin receptor–mediated (TSHR-mediated) diseases vary from loss-of-function mutations, which cause congenital hypothyroidism, to gain-of-function mutations, the primary etiologies for NAH." (PMID 38194289, 2024). "A study showed that TSHR p.F525S was the most prevalent variant in a Chinese congenital hypothyroidism." (PMID 37885353, 2024). "BACKGROUND: Loss-of-function mutations in the TSH receptor gene (TSHR) (NP_000360.2) are the potential causes of thyroid dysgenesis in patients with congenital hypothyroidism." (PMID 36842079, 2023). "In Chinese patients with congenital hypothyroidism, seven genetic variants of TSHR, such as mutations in Ile216, Ala275, Asn372, and Ser567 with loss-of-function, and genetic variants of DUOX2 are also found." (PMID 37686882, 2023). "Patients II-1, II-4, and II-5 in family A who have heterozygous R450H had mild subclinical hypothyroidism and patient III-1 who had a homozygous TSHR R450H mutation had severe congenital hypothyroidism." (PMID 29973617, 2018). "Loss of function mutations of the thyrotropin receptor (TSHR) are responsible for some forms of recessively inherited congenital hypothyroidism, either with normal or hypoplastic glands." (PMID 25146893, 2014). "The A553T mutation of TSHR found in sample 08360, has been previously been observed in two siblings with congenital hypothyroidism and was found to be inactivating." (PMID 21781349, 2011). "Congenital hypothyroidism (CH) may be caused by biallelic variants in the TSHR gene." (PMID 36468928, 2022). "Pathogenic variants in the thyroid-stimulating hormone receptor gene (TSHR) contribute to a wide spectrum of thyroid dysfunctions, ranging from congenital hypothyroidism to thyrotropin resistance." (PMID 41684033, 2026). "A defective thyroid-stimulating hormone receptor (TSHR) gene is one of the main known genetic factors leading to congenital hypothyroidism (CH)." (PMID 40391015, 2025). "In our previous studies, we have demonstrated the association of certain variants of the thyroid-stimulating hormone receptor (TSHR), thyroid peroxidase (TPO), and thyroglobulin (TG) genes with congenital hypothyroidism." (PMID 34638176, 2021). "Loss- and gain-of-function mutations in TSHR, encoding the TSH receptor, result in TSH resistance with congenital hypothyroidism (OMIM 275200) or autosomal dominant hyperthyroidism (OMIM 609152), respectively." (PMID 28853052, 2018). "Thyroid-stimulating hormone receptor (TSHR) loss-of-function (LOF) mutations lead to a wide spectrum of phenotypes, ranging from severe congenital hypothyroidism (CH) to mild euthyroid hyperthyrotropinemia." (PMID 23154162, 2013). "The TSHR gene, which is associated with thyroid dysplasia, was also selected; TSH resistance caused by loss-of-function mutations in TSHR is the most common genetic factor leading to congenital hypothyroidism." (PMID 39728398, 2024). "Interestingly, pathogenic variants in TSHR and PAX8 genes have been reported in patients with permanent congenital hypothyroidism showing reduced to normal-sized eutopic thyroid glands with low to absent radioiodide uptake on thyroid scintigraphy." (PMID 35600585, 2022). "In several cases, frameshift and/or nonsense mutations in TSHR were found in the patients with congenital hypothyroidism (CH), however they have not been functionally studied in an animal model." (PMID 29507327, 2018). "TSHR knockout (TSHR−/−) mice with congenital hypothyroidism display high-turnover osteoporosis." (PMID 29163843, 2017).
congenital hypothyroidism (continued). "This TSHR variant is 5-times more frequent in QFC than in gnomAD NFE participants and has previously been found in patients with congenital hypothyroidism and nonautoimmune hyperthyrotropinemia." (PMID 40463523, 2025). "Loss of function mutations in TSHR, PAX8, NKX2.1, NKX2.5 and FOXE1 genes are responsible for some forms of inherited congenital hypothyroidism, with or without hypoplastic thyroid." (PMID 25146893, 2014).
papillary thyroid cancer (27 papers, 1997 to 2025). "In differentiated thyroid cancer, it was observed that Thyroid-Stimulating Hormone Receptor (TSHR) is expressed not only in primary tumor, but also in metastatic sites." (PMID 40519903, 2025). "This study aimed to investigate the differences between the methylation status of TSHR and miRNA -222-3p, -221-5p, -21a-3p, and -146b-3p in the blood plasma of individuals diagnosed with papillary thyroid carcinoma (PTC) both pre- and post-surgery." (PMID 39125979, 2024). "The expression of TSHR in classical and microcarcinoma, follicular, oncocytic, PTC with focal insular component variant of papillary thyroid carcinoma." (PMID 36694763, 2023). "The relationship between the expression of TSHR and degree of invasiveness of papillary thyroid carcinoma." (PMID 36694763, 2023). "Unsurprisingly, papillary thyroid carcinomas tended to show more frequent TSHr methylation compared to benign thyroidal nodules or follicular adenomas." (PMID 26519197, 2015). "TSHr methylation rate for papillary thyroid carcinoma was only 34 % (11/32), approximately one third of our rate in PTC group reaching 90 % in our study." (PMID 26519197, 2015). "Supposedly, thyrocyte-specific transcripts such as thyroglobulin (Tg) and thyroid-stimulating hormone receptor (TSH-R) were proposed to be useful for the diagnosis of circulating tumour cells in patients suffering from differentiated thyroid carcinoma (DTC)." (PMID 16091757, 2005). "All 9 cases of papillary thyroid carcinoma with lymph node metastasis showed TSHr methylation." (PMID 26519197, 2015). "Papillary thyroid carcinomas (PTC group) significantly showed higher TSHr methylation status than benign colloidal nodules (B group, p = 0.013) and follicular adenomas (FN-B, p = 0.004) do; but no higher than in follicular carcinomas (FN-M, p = 0.115) or in AUS (p = 0.096)." (PMID 26519197, 2015). "TSHr in the methylated form is always present in metastatic papillary thyroid carcinomas, therefore TSHr methylation status may be used as a prognostic factor and as a potential predictive factor for the treatment modalities such as de-methylating agents in the future." (PMID 26519197, 2015). "Regarding to the fact that all papillary thyroid carcinomas with metastasis have shown to bear TSHr methylation in our study, patients with metastatic disease may become the first candidates for such a potential therapy with de-methylating agents in the future." (PMID 26519197, 2015). "GRK2, but not GRK5, is more highly expressed in differentiated thyroid carcinoma than normal thyroid tissue, and is involved in the rapid desensitization of thyroid-stimulating hormone receptor (TSHR), which desensitization can be further inhibited by GRK5." (PMID 33806057, 2021). "The methylation of TSHR was also confirmed by our group; we showed that after application of DNA methylation inhibitor 5-Azacytidine, TSH-R mRNA expression was increased in both normal thyroid and BCPAP papillary thyroid cancer cell lines." (PMID 28117293, 2017). "After isolation, CD133+ cells exhibited higher radioresistance and higher expression of Oct4, Nanog, Sox2, Lin28 and Glut1 in the cell line or primarily cultured papillary thyroid cancer cells, and lower expression of various thyroid-specific genes, namely NIS, Tg, TPO, TSHR, TTF1 and Pax8." (PMID 23081821, 2013). "The overall purpose of this study is to analyse the expression of Tg, thyroid-stimulating hormone receptor (TSH-R), CK 19, hTERT, and onfFN transcripts in leukocytes, as well as in papillary thyroid carcinomas (PTCs) and follicular thyroid carcinomas (FTCs), respectively." (PMID 16091757, 2005).